NEU1 (neuraminidase 1)
Diseases named in the same sentence as NEU1 in open-access papers (continued):
Sharing a sentence is not in itself a finding about the gene and the disease.
Sepsis (4 papers, 2022 to 2025). Sepsis is defined as life-threatening organ dysfunction caused by a dysregulated host response to infection. "Strikingly, although Neu1-/- mice appeared more resistant to sepsis because they experienced less weight loss, they showed higher sepsis scores." (PMID 39346907, 2024). "The results showed that the Neu1 fraction was significantly associated with the development of sepsis, as well as the disease severity." (PMID 36304125, 2022). "First, the proportion of neutrophil subtypes was inferred from the bulk RNA expression profile; and then the association between Neu1 fraction and sepsis severity was explored." (PMID 36304125, 2022). "For this purpose, we performed an in vivo inflammatory assay by inducing sepsis through LPS administration in WT and Neu1-/- mice." (PMID 39346907, 2024). "In the GSE134347 cohort, more Neu1 fraction was observed in sepsis versus healthy controls, and Neu1 fraction was able to distinguish shock from non-shock sepsis." (PMID 36304125, 2022). "Four subtypes of neutrophils were identified in the peripheral blood of sepsis, namely, the Neu1, Neu2, Neu3, and Neu4." (PMID 36304125, 2022). "Neu1 fractions were found to be an important biomarker for the severity of sepsis, as indicated by the presence of shock." (PMID 36304125, 2022). "Some biological pathways were more markedly up-regulated (severe versus mild sepsis) in Neu1 than that in other neutrophil types such as hypoxia, interferon-γ response, and TNF-α signaling via NFκB." (PMID 36304125, 2022). "Neu1 was expanded in the acute phase of sepsis on day 1, which then gradually declined during the recovery phase." (PMID 36304125, 2022). "The incoming interaction strength of Neu1 significantly declined in septic shock versus sepsis, whereas the outgoing strength was similar in both conditions." (PMID 36304125, 2022). "Additionally, we monitored the weight and the murine sepsis of mice to evaluate the effect of inflammatory induction in Neu1-/- mice." (PMID 39346907, 2024). "However, the Neu1 fraction on sepsis day 5 was still higher than the normal control subjects." (PMID 36304125, 2022). "First, a mature score of Neu1 was found to be smaller than other neutrophil types and may contain more bands than other subtypes; Neutrophil bands were found to be positively correlated with the shock severity in the eICU-CRD cohort involving more than 20,000 sepsis patients." (PMID 36304125, 2022).
Anxiety (3 papers, 2021 to 2025). Intense feelings of nervousness, tension, or panic often arise in response to interpersonal stresses. "This partial improvement of behavior could be directly linked to the increased NEU1 activity and amelioration in glutamatergic neurotransmission in the hippocampus, the brain area responsible for short-term memory and modulation of anxiety." (PMID 40540388, 2025). "We observed that both WT and Neu1-KO zebrafish formed shoaling after their transfer to the tank, probably due to anxiety." (PMID 34188220, 2021). "We further observed that the anxiety of WT fish induced a higher swimming speed compared with that exhibited by Neu1-KO zebrafish in both the black and white areas." (PMID 34188220, 2021). "Taken together, Neu1-KO zebrafish showed an excess increased interest/exploratory activity, possibly due to decreased anxiety accompanied by the downregulation of the HPA axis signaling." (PMID 34188220, 2021). "Furthermore, anxiety induction upregulated NEU1 expression in zebrafish, which is consistent with our findings." (PMID 35757207, 2022). "The low shoaling behavior in Neu1-KO fish indicated an anxiety reduction." (PMID 34188220, 2021). "In this study, we found that Neu1-KO zebrafish showed increased interactions with unfamiliar zebrafish, different fish species, and white areas, without exhibiting aggression or anxiety, although these were factors that should have been handled with caution." (PMID 34188220, 2021).
Glucose intolerance (3 papers, 2019 to 2025). Glucose intolerance (GI) can be defined as dysglycemia that comprises both prediabetes and diabetes. "Evidence from Neu1-deficient mice shows impaired insulin sensitivity and glucose intolerance without significant changes in insulin production, suggesting that NEU1 primarily affects insulin action rather than secretion." (PMID 41301440, 2025).
GM1 gangliosidosis (3 papers, 2018 to 2025). A rare lysosomal storage disorder characterized biochemically by deficient beta-galactosidase activity and clinically by a wide range of variable neurovisceral, ophthalmological and dysmorphic features. "Chronic cellular uptake of purified recombinant human b-Gal (rhb-Gal) or chronic lentiviral-mediated GLB1 overexpression in GM1 gangliosidosis patient fibroblasts coincides with profound secondary NEU1 deficiency." (PMID 31481471, 2020). "Our companion manuscript, also published in this issue of JBC, demonstrates that lysosome-targeted b-galactosidase negatively regulates neuraminidase 1 (NEU1) and promotes NEU1 deficiency in GM1 gangliosidosis." (PMID 31481471, 2020). "In contrast, a regimen of intermittent enzyme replacement therapy dosing with rhb-Gal, followed by enzyme withdrawal, is sufficient to augment b-Gal activity levels in GM1 gangliosidosis patient fibroblasts and in a mouse model of GM1 gangliosidosis without promoting NEU1 deficiency." (PMID 31481471, 2020).
idiopathic pulmonary fibrosis (3 papers, 2024). Idiopathic pulmonary fibrosis (IPF) is a nonneoplastic pulmonary disease that is characterized by the formation of scar tissue within the lungs in the absence of any known cause. "NEU1 was found upregulated in idiopathic pulmonary fibrosis (IPF)." (PMID 39596031, 2024).
rheumatoid arthritis (3 papers, 2016 to 2025). A chronic, systemic autoimmune disorder characterized by inflammation in the synovial membranes and articular surfaces. "Nevertheless, there is still no publication to show the connection between ST6Gal1, Neu 1, or ST6Gal1/Neu1 ratios and disease activity of rheumatoid arthritis until now." (PMID 40943151, 2025). "Notably, B-cell Neu1 levels are strong predictors of remission as defined by two stringent remission criteria for rheumatoid arthritis (RA), whereas B-cell ST6Gal1 levels are associated only with remission status, as defined by the 2005 modified American Rheumatism Association (ARA) criteria." (PMID 40943151, 2025). "In this study, we firstly uncover that B-cell ST6Gal1/Neu1 ratios inversely forecast the combined remission and low-disease-activity subgroup with DAS28-MCP-12 ≤ 3.6 and SDAI ≤ 11 scores for rheumatoid arthritis." (PMID 40943151, 2025). "Therefore, the ST6Gal1/Neu1 ratio is a potential predictor for remission or combined remission and low disease activity for DAS28-MCP-1 and SDAI assessment in rheumatoid arthritis, pending confirmation by other studies." (PMID 40943151, 2025).
schizophrenia (3 papers, 2018 to 2025). A major psychotic disorder characterized by abnormalities in the perception or expression of reality. "The microglial H-MAGMA-risk genes BAG6, NEU1, PRRC2A, PSMB8, PSMB8-AS1 and PSMB9 were associated with MS, ALS and schizophrenia." (PMID 40202986, 2025).
sialidosis type II (3 papers, 2020 to 2023). "Sialidosis, Type II (OMIM #256550) is caused by a mutation of NEU1 (Neuraminidase-1), leading to the lysosomal accumulation of sialylated glycopeptides and oligosaccharides, manifesting in gait disturbances, corneal clouding and psychomotor retardation." (PMID 32351971, 2020).
Thrombocytopenia (3 papers, 2020 to 2024). A reduction in the number of circulating thrombocytes. "In prolonged isolated thrombocytopenia (PT), Neu1 and its translocation play a role in allogeneic hematopoietic stem cell transplantation (HSCT)." (PMID 39128726, 2024). "More recently, desialylation of platelets by NEU1 has been shown to play critical role in platelet clearance and thrombocytopenia." (PMID 33392200, 2020). "In acquired Glanzmann thrombasthenia, which occurs in those with bleeding complications even though they do not have thrombocytopenia, autoantibodies target the Iib3 integrin receptor, causing Neu1 translocation to the platelet cell surface." (PMID 39128726, 2024).
amyloidosis (2 papers, 2024 to 2025). A disorder characterized by the localized or diffuse accumulation of amyloid protein in various anatomic sites. "NEU1 deficiency in mice induces a spontaneous phenotype of AD-like amyloidosis, while overexpression of NEU1 obtained by injecting NEU1 into the brain of an AD mouse model was conducive to a reduction in amyloid plaques." (PMID 40943651, 2025). "Experimentally, NEU1 deficiency in mice induces a spontaneous phenotype of AD-like amyloidosis, while the overexpression of NEU1 is conducive to a reduction in amyloid plaques." (PMID 39194692, 2024).
Ataxia (2 papers, 2020 to 2024). Ataxia refers to impaired coordination of voluntary muscle movement. "In our study, five patients (2.5%) were positive for the NEU1 gene screen in a cohort of 202 undiagnosed ataxia patients." (PMID 39482827, 2024). "Thus, when a patient with ataxia tests negatively in screening for the relatively common spinocerebellar ataxias types, NEU1 genetic screening should be considered." (PMID 39482827, 2024).
autoimmune disease (2 papers, 2023 to 2024). A disorder resulting from loss of function or tissue destruction of an organ or multiple organs, arising from humoral or cellular immune responses of the individual to their own tissue constituents. "CYP21A2, as well as MSH5, PPP1R18, and NEU1 have been demonstrated by previous GWASs associated with other autoimmune disorders such as RA, ankylosing spondylitis (AS), T1DM, and SLE." (PMID 37197658, 2023). "Four genes (BLK, HSPA1A, IL12A, NEU1) have been targeted for drug development in autoimmune diseases and other conditions." (PMID 38997544, 2024).
colorectal cancer (2 papers, 2012 to 2021). A primary or metastatic malignant neoplasm that affects the colon or rectum. "Interestingly, among intrinsic growth gene eQTLs, we found two well replicated colorectal cancer SNPs (rs4779584 and rs3802842), which target growth-associated genes NEU1 and MED13; both genes have been implicated in colorectal cancer." (PMID 22346769, 2012).
endotoxemia (2 papers, 2014 to 2019). "The significant reduction of endotoxemia in mice with Neu1-deficient hematopoietic cells suggests that endogenous sialidase may be a valuable therapeutic target." (PMID 25187624, 2014). "In fact, Neu1 deletion provided resistance to endotoxemia, and sialidase inhibitors were able to protect mice against it." (PMID 31791382, 2019). "Together, our data reveal an overlooked network of interactions among Siglecs, host sialidases and TLRs and, with more potent Neu1 inhibitors, propose host sialidases as therapeutic targets for lethal endotoxemia." (PMID 25187624, 2014). "Indeed, we showed that inhibition of Neu1 by either gene deletion or sialidase inhibitor administration confers a strong protection against endotoxemia." (PMID 25187624, 2014). "Therefore, Neu5Gc2en protects mice against endotoxemia by targeting Neu1." (PMID 25187624, 2014). "Here we report a critical role for Neu1 in regulating Siglec-TLR interaction and endotoxemia." (PMID 25187624, 2014). "Absence of Neu1 in hematopoietic cells or systematic treatment with sialidase inhibitor Neu5Gc2en protected mice against endotoxemia." (PMID 25187624, 2014). "Since we showed Neu1 to be a key regulator of Siglec-E-TLR4 interaction and of the TLR4 function in vitro, we sought a genetic model to definitively address the potential role of Neu1 in the host response to endotoxemia." (PMID 25187624, 2014).
gastric cancer (2 papers, 2025). A primary or metastatic malignant neoplasm involving the stomach. "In bladder and gastric cancers, NEU1 overexpression promotes tumor cell apoptosis." (PMID 40221400, 2025).
ischemia (2 papers, 2020 to 2022). A hypoperfusion of the BLOOD through an organ or tissue caused by a PATHOLOGIC CONSTRICTION or obstruction of its BLOOD VESSELS, or an absence of BLOOD CIRCULATION. "Therefore, NEU1 specific inhibition and, more specifically, inhibition of the NEU1/β-GAL/PPCA complex could be developed into novel therapies to limit myocardial damage and dysfunction after ischemia and reperfusion injury." (PMID 32975669, 2020).
liver cancer (2 papers, 2021 to 2025). An epithelial or non-epithelial malignant neoplasm that arises from the liver. "Aberrant expression of NEU1 has been linked to the progression of numerous malignancies, including liver cancer." (PMID 40196362, 2025). "Patients with liver cancer exhibiting high levels of NEU1 expression tended to have a less favorable prognosis." (PMID 40196362, 2025). "Our findings provide new directions on the role of NEU1 in liver cancer and offer latent strategies to address the chemotherapy-induced drug resistance." (PMID 40196362, 2025). "The result showed that there were four datasets with high expression of NEU1 in liver cancer, and these datasets comprised a total of 712 samples (386 HCC samples and 326 normal samples)." (PMID 34513919, 2021). "The result of CCLE analysis revealed that mRNA expression level of NEU1 in cell lines of liver cancer listed the first highest among all tumor types." (PMID 34513919, 2021). "NEU1 knockdown inhibited liver cancer cells proliferation, invasion and migration." (PMID 40196362, 2025). "Notably, OP (NEU1 inhibitor), promoted lipophagy, thereby inhibiting liver cancer proliferation and tumorigenesis." (PMID 40196362, 2025). "Additionally, the mRNA and protein expression levels of NEU1 were increased in liver cancer cell lines and HCC tissues, respectively." (PMID 34513919, 2021). "Moreover, the enhanced expression of NEU1 was confirmed in liver cancer cell lines, and we also found that NEU1 protein expression was upregulated in HCC tissues compared with normal tissues (HPA)." (PMID 34513919, 2021).
lung carcinoma (2 papers, 2023 to 2024). "The association between abnormally high expression of Neu1 and poor prognosis of lung cancer needs further investigation." (PMID 38500102, 2024). "It has been proved deglycosylation by neuraminidase induced CD44-HA binding in human lung cancer cell lines, but whether NEU1 is the key neuraminidase for HA deglycosylation in lung cancer remains unclear." (PMID 38500102, 2024). "NEU1 was also identified to be correlated with levels of drug resistance in lung cancer." (PMID 38500102, 2024).
lung disease (2 papers, 2024). "While the exact mechanisms by which Neu1 contributes to lung disease are not yet fully understood, it is believed that Neu1 plays a role in the regulation of cell signaling pathways, inflammation, and extracellular matrix remodeling." (PMID 38500102, 2024).
melanoma (2 papers, 2014 to 2024). A malignant, usually aggressive tumor composed of atypical, neoplastic melanocytes. "Consistently, knockdown NEU1 restricts the in vitro proliferation and migration capacity in melanoma cells, with similar effects in vivo against melanoma progression." (PMID 39194692, 2024). "The expression of NEU1 is positively correlated with overall survival in melanoma patients." (PMID 39194692, 2024). "NEU1 expression levels predicate the infiltration of immune cells in melanoma in vivo." (PMID 39194692, 2024). "Similarly, NEU1 was found to be highly expressed in melanoma samples compared to normal samples." (PMID 39194692, 2024).
Myocardial fibrosis (2 papers, 2022). "PSR data showed that NEU1 deficiency mice significantly attenuated myocardial fibrosis caused by MI compared with mice injected with shRNA." (PMID 35548408, 2022).
prion disease (2 papers, 2014 to 2015). A transmissible disease that is caused by a protein that is able to induce abnormal folding of normal cellular proteins, leading to characteristic spongiform brain changes, which are associated with neuronal loss without an inflammatory response. "Because the life-span of Neu1−/− mice is limited to ∼150 days, it was not possible to test whether knocking out Neu1 affected the incubation time to prion disease." (PMID 25211026, 2014).
prostate carcinoma (2 papers, 2021 to 2025). A carcinoma that arises from epithelial cells of the prostate gland. "In nude mice bearing PC‐3 human prostate cancer xenografts, DOX treatment significantly downregulated NEU1 expression while concomitantly increasing SIRT1 protein levels in tumor lysates." (PMID 40411250, 2025).
acute kidney injury (1 paper, 2023). Sudden and sustained deterioration of the kidney function characterized by decreased glomerular filtration rate, increased serum creatinine or oliguria. "Immunofluorescence showed that the increase of NEU1 content was mainly co-localized with kidney injury molecule 1 (KIM1), a biomarker of injured epithelial cells in acute kidney injury and CKD32,33." (PMID 36973294, 2023).
Aortic Rupture (1 paper, 2021). The tearing or bursting of the wall along any portion of the AORTA, such as thoracic or abdominal. "Deletion of NEU1 (either global or specifically in macrophage) all manifested improved aorta function, vascular remodeling, and decreased mortality due to aortic rupture." (PMID 34869700, 2021). "Global or macrophage-specific NEU1 knockout (NEU1 CKO) mice had no baseline aortic defects but manifested improved aorta function, and decreased mortality due to aortic rupture." (PMID 34869700, 2021).
Arrhythmia (1 paper, 2020). Any cardiac rhythm other than the normal sinus rhythm. "In this regard, after I/R, NEU1 in macrophages promoted enhanced and prolonged inflammation, and in cardiomyocytes NEU1 impaired the expression of the gap junction protein Connexin-43 (CX43) and promoted arrhythmias and LV dysfunction." (PMID 32975669, 2020).
Arthritis (1 paper, 2021). Inflammation of a joint. "We observed in STIA that neither zanamivir treatment nor oseltamivir (data not shown), an inhibitor of NEU1, ameliorated arthritis, although this model depends on the extravasation of inflammatory cells such as neutrophils through the endothelium into joints." (PMID 33572654, 2021).
atopic asthma (1 paper, 2015). An asthma that is characterized by symptoms that are triggered by an allergic reaction caused by inhaled allergens such as dust mite allergen, pet dander, pollen and mold. "Among the genes identified in the present study (M6PR, TPP1, GLB1, NEU1, ACP2, LAMP1 and HGSNAT) that were significantly associated with lysosomal function, only TPP1 has been confirmed as being associated with atopic asthma." (PMID 25633562, 2015).
atrial fibrillation (1 paper, 2026). A disorder characterized by an electrocardiographic finding of a supraventricular arrhythmia characterized by the replacement of consistent P waves by rapid oscillations or fibrillatory waves that vary in size, shape and timing and are accompanied by an irregular ventricular response. "Neuraminidase 1 (NEU1) regulation of atrial fibrillation (AF) progression via fibrosis remains unknown." (PMID 41914737, 2026).
autism (1 paper, 2022). Persistent deficits in social interaction and communication and interaction as well as a markedly restricted repertoire of activity and interest as well as repetitive patterns of behavior. "Correlation of NEU1 gene expression results to Autism Diagnostic Observation Schedule, Second Edition (ADOS-2), Social Affect (SA), and Restricted and Repetitive Behavior (RRB) in children with ASD." (PMID 35757207, 2022).
bladder tumor (1 paper, 2020). "The dysregulated expression of NEU1 in these clinical samples provides further evidence for a link between NEU1 expression and bladder tumor progression." (PMID 32164705, 2020).
brain ischemia (1 paper, 2017). Diminished or absent blood supply to the brain caused by obstruction (thrombosis or embolism) of an artery resulting in neurologic damage. "This may be consistent with delayed neuronal loss after brain ischemia being due to Gal-3–, Neu1-, and MerTK-mediated microglial phagocytosis." (PMID 28500071, 2017).